PIK3C2B (phosphatidylinositol-4-phosphate 3-kinase catalytic subunit type 2 beta)
Description:
Phosphorylates PtdIns and PtdIns4P with a preference for PtdIns. Does not phosphorylate PtdIns(4,5)P2. May be involved in EGF and PDGF signaling cascades.
Synonyms: C2-PI3K; PI3K-C2beta
Tractability: Small molecule: a high-quality ligand is known; it belongs to a druggable protein family. Antibody: UniProt places it where antibodies can reach, with high confidence; its Gene Ontology location is reachable by antibodies, with high confidence. PROTAC: ubiquitination databases record sites on it; its protein half-life has been measured; a small molecule that binds it is known.
Target class: Enzyme; Transferase
Gene: Protein-coding gene on chromosome 1 (204,422,628 to 204,494,805, reverse strand). Ensembl gene ENSG00000133056.
Subcellular location: Microsome; Cell membrane; Cytoplasm, cytosol; Nucleus; Endoplasmic reticulum
Subcellular location (Human Protein Atlas): Nuclear membrane; Nucleoplasm; Cytosol
Pathways (Reactome):
Metabolism: Synthesis of PIPs at the plasma membrane
Gene Ontology:
Molecular function: 1-phosphatidylinositol-3-kinase activity; 1-phosphatidylinositol-4-phosphate 3-kinase activity; protein binding; kinase activity; lipid kinase activity; phosphatidylinositol binding
Biological process: cell migration; phosphatidylinositol 3-kinase/protein kinase B signal transduction; phosphatidylinositol-3-phosphate biosynthetic process; phosphatidylinositol-mediated signaling; phosphatidylinositol phosphate biosynthetic process
Cellular component: cytosol; intracellular membrane-bounded organelle; plasma membrane; endocytic vesicle; endoplasmic reticulum; nucleus
Genetic constraint (gnomAD): Loss-of-function variants: 73 observed, 159.3 expected, observed/expected ratio (o/e) 0.46, 90% interval 0.38 to 0.56. The upper end of that interval is the gene's LOEUF score, 0.56, which puts it in group 2 of 6, group 1 being the genes least tolerant of losing a copy. Missense variants: 1,612 observed, 1,990 expected, observed/expected ratio (o/e) 0.81, 90% interval 0.78 to 0.84. Synonymous variants: 724 observed, 800.22 expected, observed/expected ratio (o/e) 0.9, 90% interval 0.85 to 0.96.
Homologues: Orthologues: chimpanzee PIK3C2B (99% identical), macaque PIK3C2B (99% identical), pig PIK3C2B (95% identical), dog PIK3C2B (94% identical), mouse Pik3c2b (94% identical), guinea pig PIK3C2B (93% identical), rat Pik3c2b (93% identical), rabbit PIK3C2B (87% identical), zebrafish pik3c2b (62% identical), Drosophila melanogaster Pi3K68D (34% identical), Drosophila melanogaster Pi3K92E (17% identical), Caenorhabditis elegans piki-1 (17% identical), and 1 more. Paralogues in human: PIK3C2A (46% identical), PIK3C2G (31% identical), PIK3CD (18% identical), PIK3CA (17% identical), PIK3CG (17% identical), PIK3CB (17% identical), PI4KA (16% identical), PIK3C3 (12% identical), PI4KB (9% identical).
Diseases named in the same sentence as PIK3C2B in open-access papers:
PIK3C2B is named in the same sentence as 48 diseases in open-access papers, as found by Europe PMC text mining. Sharing a sentence is not in itself a finding about the gene and the disease. The quoted sentences say what the papers report.
breast carcinoma (8 papers, 2013 to 2024). "A late mutation was found in PIK3C2B which interacts with PIK3CA, one of the most frequent mutations that has been reported in breast cancer." (PMID 25729435, 2015). "The strongest gene-based association was PLCD1 for pancreatic cancer and prostate cancer, PIK3C2B for breast cancer, and INPP5K for bladder cancer, respectively." (PMID 25683757, 2015). "Only imputed SNP rs12404974, located between PIK3C2B and MDM4 (r2 = 0.77 with rs4951407), was more significantly associated with breast cancer (P = 2.7×10−6) than any of the genotyped SNPs." (PMID 23544013, 2013). "Here, EVs from eribulin-breast cancer cells contained higher levels of PIK3R5 (log2FC = +3.877), PIK3C2B (log2FC = +1.664) and PIK3R1 (log2FC = +1.500) mRNAs than controls." (PMID 38534323, 2024). "Other genes associating with this component were CHD3 in bladder cancer, HERC2 in ovary cancer, PIK3C2B in lung squamous cell cancer, EP300 in skin cancer (and breast cancer at a FDR of 2%), RBBP5 in pan-cancer, and SMC1B in pan-cancer." (PMID 35764656, 2022). "Through correlation analysis of gene expression profiles between candidate genes and miR-148a in the TCGA breast cancer patient database, we further narrowed down targets of miR-148a to four genes, INHBB, PIK3C2B, WNT1 and NRP1." (PMID 26967387, 2016).
ovarian carcinoma (6 papers, 2016 to 2022). A malignant neoplasm originating from the surface ovarian epithelium. "Further, the ovarian cancer dataset from Kaplan Meier Plotter was used to test for the survival prediction capacity of PIK3C2B, and we found that PIK3C2B is associated with poor overall survival and progression free survival in endometrioid ovarian cancer patients but not in HGSOC." (PMID 35205706, 2022). "We also observed that PIK3C2B is highly amplified in ovarian cancer patients and ovarian cancer is one of the cancers where PIK3C2B was expressed in modest to high level in the TCGA dataset." (PMID 35205706, 2022). "In ovarian cancer, knockdown of PIK3C2B significantly inhibited the formation of lamellipodia and reduced the number of metastasis in human cancer cell xenografts." (PMID 30884740, 2019). "Interestingly we found that AKT3 and PIK3C2B were 32% and 27% significantly higher, respectively, in ovarian cancer datasets." (PMID 35205706, 2022). "Moreover, the study showed that treatment with ceramide liposomes, which are believed to have multiple activities against the progression of ovarian cancer, reduced cell migration by affecting PIK3C2B compartmentalization." (PMID 30884740, 2019). "In ovarian cancer, copy number gains of PIK3C2B have been reported as well." (PMID 29088297, 2017). "Other amplified oncogenes frequently found in epithelial ovarian cancer were ERBB2, STAT3, PIK3C2B, CDK2, and CDK4, as well as SWI/SNF chromatin modification complex genes, including ARID1A and SMARCC1." (PMID 36430324, 2022). "Next, we checked the putative copy number alteration and mRNA expression of PIK3C2B from GISTIC software and found a significant trend of PIK3C2B gain and amplification in ovarian cancer patients." (PMID 35205706, 2022).
prostate carcinoma (6 papers, 2011 to 2023). A carcinoma that arises from epithelial cells of the prostate gland. "A significant association between PIK3C2B and familial, early-onset prostate cancer has been observed." (PMID 38102712, 2023). "The authors examined the association between several SNPs in PI3Ks genes (PIK3CD, PIK3C2A, PIK3R3, PIK3AP1, and PIK3C2B) and prostate cancer risk: among the five genes, only PIK3C2B showed a cluster of SNPs related to prostate cancer risk." (PMID 23658859, 2013). "In that study, rs7556371, a SNP of PIK3C2B, was shown to be associated with increased prostate cancer risk." (PMID 21373201, 2011). "For example, fostamatinib, targeting PIK3C2B, has been used for the treatment of chronic immune thrombocytopenia; and estramustine, targeting MAP2, has been used for prostate cancer." (PMID 38102678, 2023). "Common genetic alterations within the three prostate cancer datasets analyzed were observed in PTEN, DEPTOR, SGK3, FOXO1/3, MAP3K7, RRAGD, SESN1, PIK3CA, PIK3C2B, and PDPK1." (PMID 32630372, 2020).
glioma (5 papers, 2020 to 2024). A benign or malignant brain and spinal cord tumor that arises from glial cells (astrocytes, oligodendrocytes, ependymal cells). "The GISTIC 2.0 assessment uncovered numerous remarkable amplified regions containing multiple oncogenes in glioma patients with higher risk scores, consisting of 1q32.1 (PIK3C2B), 12q14·1(CDK4), 7p11·2 (EGFR), and 4q12 (PDGFRA)." (PMID 36311792, 2022). "GISTIC 2.0 analysis identified several significant regions of amplification harboring multiple oncogenes in gliomas with a high-risk score, including 1q32.1 (PIK3C2B), 4q12 (PDGFRA), 7p11·2 (EGFR), and 12q14·1(CDK4)." (PMID 32023222, 2020). "The mutation frequency of PIK3C2B in high-grade gliomas is unknown." (PMID 39767683, 2024). "According to the Stupp protocol and metronomic dose of the temozolomide treatment, the mutated genes related to the second relapse of patients with high-grade glioma were PIK3C2B, KIT, ERBB3, and MLH1." (PMID 39767683, 2024). "Furthermore, amplification peaks of oncogenes (PIK3C2B, PDGFRA, EGFR, CDK4), and deletion peaks of tumor suppressor genes (TUSC1, CDKN2A, CDKN2B, PTEN, FAS, BNIP3) were detected in the gliomas with a high risk score." (PMID 32023222, 2020). "Oncogenic drivers including PIK3C2B, EGFR, and CDK4 are amplified in gliomas with low TOX expression." (PMID 32762688, 2020).
glioblastoma (4 papers, 2014 to 2017). The most malignant astrocytic tumor (WHO grade IV). "PIK3C2B was considered to be a possible cause of resistance to erlotinib during the later stages of glioblastoma, i.e. it may become a driver in tumors that have evolved beyond a certain point." (PMID 25236784, 2014). "Gain at 1q32.1, the chromosomal region encoding for PIK3C2B and MDM4 has been reported in studies assessing copy-number alterations in glioblastoma multiforme." (PMID 29088297, 2017).
lung adenocarcinoma (2 papers, 2017 to 2025). A carcinoma that arises from the lung and is characterized by the presence of malignant glandular epithelial cells. "Elevated expression of PIK3C2B was correlated with reduced overall survival (log-rank p < 0.05) and shorter disease-free survival (p < 0.05) in lung adenocarcinoma patients." (PMID 41362647, 2025). "Notably, our demonstration of PIK3C2B's pro-migratory effects in lung adenocarcinoma cells complements emerging evidence that class II PI3Ks regulate membrane remodeling, though this mechanism warrants further exploration." (PMID 41362647, 2025). "•High PIK3C2B correlates with poor survival and stage-dependent progression in lung adenocarcinoma." (PMID 41362647, 2025). "The PI3K protein family acted as critical roles in the lung adenocarcinoma, since the components of the PI3K protein family include PIK3C2B, PIK3CA, PIK3R1 and so forth were presented in the intersections." (PMID 28503373, 2017). "PIK3C2B expression showed significant positive correlations with key EMT regulators: SNAI1 (r = 0.11, p = 0.00098), VIM (r = 0.21, p = 1e-10), ZEB1 (r = 0.37, p = 6.7e-33), and TWIST2 (r = 0.11, p = 0.00034) in TCGA lung adenocarcinoma samples." (PMID 41362647, 2025).
lung carcinoma (2 papers, 2023 to 2025). "To investigate the metabolic reprogramming associated with PIK3C2B in lung cancer cells, we employed the Seahorse extracellular flux analyzer to measure bioenergetic parameters." (PMID 41362647, 2025). "In this study, we employed integrative transcriptomics approaches to identify PIK3C2B as a novel metastasis-associated gene in lung cancer." (PMID 41362647, 2025). "•PIK3C2B is a novel metastasis-associated gene in lung cancer identified by cross-dataset transcriptomics." (PMID 41362647, 2025). "PCR also illustrated the association in PIK3C2B-knocked-down lung cancer cells." (PMID 41362647, 2025). "Morever, PCR further confimed the association in PIK3C2B-knocked-down lung cancer cells." (PMID 41362647, 2025). "This study identifies PIK3C2B as a pivotal regulator of lung cancer progression, bridging metastatic dissemination and metabolic adaptation—a nexus that remains underexplored in oncology." (PMID 41362647, 2025). "To investigate the functional role of PIK3C2B in lung cancer progression, we utilized RNA interference to silence PIK3C2B in lung cancer cell lines." (PMID 41362647, 2025). "Our findings establish PIK3C2B as a prognostic biomarker and a potential metabolic target in lung cancer." (PMID 41362647, 2025). "While our findings illuminate a correlation between PIK3C2B expression, metabolic flexibility, and EMT, it is important to frame these observations as preliminary evidence suggesting PIK3C2B's potential role in lung cancer progression." (PMID 41362647, 2025). "Our findings establish PIK3C2B as a dual-function oncoprotein that promotes lung cancer progression through EMT activation and bioenergetic reprogramming." (PMID 41362647, 2025). "To explore the potential anti-tumor targets of apatinib, we have examined all tyrosine kinases and important silk/threonine kinases associated with lung cancer including Akt 1-3, FRAP1, PIK3C2A, PIK3C2B, BRAF, BRAF V600E and RAF1 in the Life platform." (PMID 36759818, 2023).
myotubular myopathy (2 papers, 2023). "Overall, the homozygous Pik3c2b kinase-dead mutation extents the lifespan and normalizes muscle atrophy and muscle force of the myotubular myopathy KO/WT mice." (PMID 36943412, 2023).
neuroblastoma (2 papers, 2018 to 2022). Neuroblastoma (NB) is the most common solid, extracranial childhood tumor. "Previously, miR-362-5p was reported to represses neuroblastoma malignancy by targeting phosphatidylinositol-4-phosphate 3-kinase catalytic subunit type 2 beta (PI3K-C2β)." (PMID 35365168, 2022). "miR-362-5p could be used as a tumor suppressor by targeting PIK3C2B, which inhibited the proliferation and migration of neuroblastoma." (PMID 30155491, 2018).
acute myeloid leukemia (1 paper, 2022). Acute myeloid leukemia (AML) is a group of neoplasms arising from precursor cells committed to the myeloid cell-line differentiation. "It is worth to mention that a few genes with a role in acute myeloid leukemia: GRB2, CSFIR, MARCKS and PDGFB were upregulated; FLT1, IL6, PIK3C2B, BALAP3 and MAPK10 were downregulated." (PMID 36413544, 2022).
fallopian tube carcinoma (1 paper, 2024). A carcinoma that arises from epithelial cells of the fallopian tube. "A report at the 2016 ASCO meeting showed a cohort of 379 patients with ovarian or fallopian tube carcinoma have been evaluated for 10 genes AKT1, AKT2, AKT3, mTOR, PIK3CA, PIK3C2B, PIK3R1, PTEN, TSC1, TSC2 in the PI3K/AKT/mTOR pathway." (PMID 38167649, 2024).
head and neck squamous cell carcinoma (1 paper, 2022). A squamous cell carcinoma that arises from any of the following anatomic sites: lip and oral cavity, nasal cavity, paranasal sinuses, pharynx, larynx, and salivary glands. "While PIK3CA mutations are frequent in head and neck squamous cell carcinomas, mutations involving PIK3CB or PIK3C2B are relatively rare." (PMID 36362284, 2022).
hypophosphatemia (1 paper, 2025). Lower than normal levels of phosphates in the circulating blood. "However, according to our knowledge, PIK3C2B has not been previously linked to hypophosphatemia, and we regarded the variant as an unlikely cause for the severe hypophosphatemia in our family." (PMID 39877728, 2025).
leukemia (1 paper, 2020). A malignant (clonal) hematologic disorder, involving hematopoietic stem cells and characterized by the presence of primitive or atypical myeloid or lymphoid cells in the bone marrow and the blood. "As the knockdown of PIK3C2B in human leukemia CCRF-CEM cells decreased sensitivity to 6-TG in comparison to control, lacking or reduced expression of Pik3c2b mRNA in 4T1 might explain the resistance to 6-TG treatment." (PMID 32793490, 2020).
mastitis (1 paper, 2022). Inflammation of breast tissue during lactation or postpartum due to an obstructed duct or infection. "In our study, a total of 32 AS SNPs were identified, of which two SNPs rs42705933 and rs133847062 had completely different genotypes between healthy cows and subclinical mastitis cows, which corresponded to SE events of PIK3C2B and PRPF8." (PMID 36204322, 2022). "Specifically, SNP rs42705933 on chromosome 16 at 2,210,365 bp of gene PIK3C2B had the genotype AA in healthy cows and AG in subclinical mastitis cows." (PMID 36204322, 2022). "It is hypothesized that the PIK3C2B and PPRPF8 splice variants associated with AS SNPs (rs42705933 and rs133847062) may be risk factors for susceptibility to bovine subclinical mastitis." (PMID 36204322, 2022).
meningioma (1 paper, 2023). A generally slow growing tumor attached to the dura mater. "Important driver mutations specifically associated with meningioma pathology (including NF2, TRAF7, SMO, PIK3C2B and AKT1) that were identified in the tissues were consistently found in spheroids." (PMID 38102708, 2023).
metastatic colorectal cancer (1 paper, 2025). "This parallels recent findings in patients with metastatic colorectal cancer, where PIK3C2B mutations exhibited adverse outcomes, suggesting a conserved role across malignancies." (PMID 41362647, 2025).
metastatic tumour (1 paper, 2021). "The primary and metastatic tumours demonstrated the somatic mutations FBXW7 Q242H, FBXW7 S582L as well as KDM6A S763I and PIK3C2B Q877_W878K, suggesting the possibility of bi-allelic FBXW7 loss resulting in a high level of MYC protein expression, which was documented in the metastatic tumour." (PMID 33311588, 2021).
Parkinson disease (1 paper, 2016). A progressive degenerative disorder of the central nervous system characterized by loss of dopamine producing neurons in the substantia nigra and the presence of Lewy bodies in the substantia nigra and locus coeruleus. "Our study,therefore, revealed that ROP altered gene expression in SH-SY5Y cells, and futureinvestigation of PIK3C2B and other loci on chromosome 1 may providelong-term implications for identifying novel target genes of Parkinson's disease." (PMID 26785691, 2016).
Sepsis (1 paper, 2024). Sepsis is defined as life-threatening organ dysfunction caused by a dysregulated host response to infection. "Collectively, these results pinpoint NFKBIA, NFKB2, TNFSF14, DUSP2, and PIK3C2B as key mediators of DcR3’s broad-spectrum effects in CLP-induced sepsis." (PMID 38700314, 2024).
Stroke (1 paper, 2025). Sudden impairment of blood flow to a part of the brain due to occlusion or rupture of an artery to the brain. "HTR3D and NEUROG3 were linked with the susceptibility of PSD and PIK3C2B with stroke in the Chinese Han population." (PMID 40529498, 2025).
tuberculosis (1 paper, 2018). A chronic, recurrent infection caused by the bacterium Mycobacterium tuberculosis. "Blood transcriptomics of patients with tuberculosis revealed that that PIK3C2B is downregulated when compared to individuals with latent tuberculosis infection." (PMID 30065729, 2018).